TGFB1 (transforming growth factor beta 1)
Diseases named in the same sentence as TGFB1 in open-access papers (continued):
Sharing a sentence is not in itself a finding about the gene and the disease.
liver fibrosis (continued). "Detection of the mRNA levels of a series of liver fibrosis-related molecules: Acta2, Col1a1, Tgfb1, and Timp1 in livers from IL-21−/−p40−/−IL-2Ra−/− mice and controls suggested no significant change of liver fibrosis." (PMID 35300072, 2022). "Affected by the pro-inflammatory milieu, Ito cells cease to express BAMBI which normally inhibits TGFβ1-signaling, thus increasing the sensitivity of Ito cells to the TGFβ1-mediated activation and ultimately contributing to the development of liver fibrosis." (PMID 36077265, 2022). "Angiotensin II type 1 receptor (AT1R) is expressed in activated HSCs, and angiotensin II (Ang II) enhances hepatic fibrosis through the production of transforming growth factor-beta 1 (TGF-β1)." (PMID 35328352, 2022). "TGFβ1 is an important pro-fibrogenic factor and a direct marker for the evaluation of liver fibrosis, and α-SMA is a reliable marker for HSC activation." (PMID 35517817, 2022). "Blockade of Mas receptor enhances liver fibrosis by increasing the liver content of collagen and TGFβ1." (PMID 35629915, 2022). "Next, we determined the target cell type of LSEC‐derived A‐FABP that is responsible for TGFβ1 production contributing to liver fibrosis." (PMID 34105268, 2021). "Transforming growth factor β 1 (TGFβ1) is the main pro-fibrosis factor, and the TGF-β/Smad signaling pathway is the most important intracellular signaling pathway in the occurrence and development of liver fibrosis." (PMID 34597331, 2021). "Oxidative stress and increased production of transforming growth factor-beta 1 (TGF-β1) are believed to be key mechanisms in the development of liver fibrosis." (PMID 33498614, 2021). "In a mouse model, constitutive expression of TGFB1 in the liver results in extensive hepatic fibrosis." (PMID 34771552, 2021). "We set up an in vitro model of hepatic fibrosis using a human hepatic stellate cell line (LX-2) activated by transforming growth factor-beta 1 (TGF-β1)." (PMID 34796180, 2021). "We reported in previous paper that the first step to liver fibrosis in response to injury is the TGFβ1-induced TIF1γ suppression in the activated HSC." (PMID 33407858, 2021). "Overall, CAVIN2+ Kupffer cells were the main source of TGFB1, consisting primarily of mononuclear phagocytes in the livers of the SJ group subjects and potentially playing an irreplaceable role in hepatic fibrosis of schistosomiasis." (PMID 34355810, 2021). "In liver fibrosis, TGFβ1 upregulates p-Smad2/3, Jagged1, Notch1 and Hes1, leading to trans-differentiation of hepatic stellate cells into myofibroblast cells." (PMID 32724452, 2020). "The observed sevelamer-mediated attenuation of hepatic fibrosis coincided with a decline in the hepatic expression levels of profibrotic genes including Col1a1, Acta2, and Tgfb1." (PMID 32575352, 2020). "The role played by this protein in TGFRs trafficking and TGFβ1 signaling remains controversial, and its expression tends to decrease in liver fibrosis." (PMID 32092977, 2020). "Leptin administration has been shown to enhance liver fibrosis by increasing the expression of procollagen-I, TGFβ1 and smooth muscle actin and amplify inflammation by increasing the systemic levels of TNF-α in experimental models." (PMID 32933141, 2020). "Transforming growth factor beta 1 (TGF-β1) up-regulated in liver fibrosis and known to down-regulate miR-29b through SMAD3 pathway." (PMID 32513194, 2020). "The authors demonstrated significant downregulation of mRNA levels of procollagen I, TIMP 1, and TGFβ1 in rats with BDO-induced liver fibrosis administered silymarin." (PMID 32168847, 2020). "We demonstrated that myricetin attenuated liver fibrosis in mice via modulating TGFβ1 and Akt signaling and shifting Th1/Th2 balance." (PMID 32373112, 2020).
liver fibrosis (continued). "The present in vivo and in vitro researches demonstrated that SREBP1c exerted inhibitory effect on TAA‐induced liver fibrosis and down‐regulated TGFβ1 level." (PMID 32678475, 2020). "Pathogenesis of liver fibrosis induced by hepatic inflammation is initiated with the release of apoptotic bodies, cytokines, and growth factors (TGFβ1, TNF-α, EGF, IGF) from injured hepatocytes." (PMID 32635162, 2020). "Angiotensin II induces the release of vascular endothelial growth factor (VEGF) and enhances hepatic fibrosis through the production of transforming growth factor-beta 1 (TGF-β1) by Kupffer and activated stellate cells." (PMID 33050084, 2020). "The results showed that the relative mRNA expression level of mouse TGFb1 was increased after CCl4-induced liver fibrosis compared to the baseline value in the control group and was not changed significantly in cirrhosis compared to the control." (PMID 30631109, 2019). "Previous studies have shown that TGFB1 is one of the main molecules orchestrating hepatic fibrosis after F. hepatica infection in sheep and in cattle." (PMID 31555289, 2019). "Fermented black radish was also shown to mitigate liver fibrosis through the inhibition of alpha‐smooth muscle actin, transforming growth factor beta‐1, and collagen type I alpha 1 chain." (PMID 31660146, 2019). "Hong-wei Zhao showed that OM played a significant antifibrotic role via modulation of TLR4-dependent inflammatory and TGFβ1-signaling pathways in CCL4 induced hepatic fibrosis rats." (PMID 31221141, 2019). "LIG prevents and alleviates the development of liver fibrosis by downregulating TGFβ1, TβRII, CCN2, and Smad2/3, and type I collagen while upregulating Smad7 and inhibits proliferation of hepatic stellate cells." (PMID 31886227, 2019). "Results presented in literature underline the beneficial effect of syndecan-1 in the early stages of liver fibrosis, by way of binding and enhancing the clearance of TGFβ1, an important promoter of fibrogenesis." (PMID 31815014, 2019). "The chains of syndecan-1 are binding several molecules, facilitating intercellular signalling, the most important interactions in liver fibrosis being the ones with TGFβ1, basic fibroblast growth factor (bFGF), and hepatocyte growth factor (HGF)." (PMID 31815014, 2019). "Similar to the CCl4-induced fibrosis model, Med23 silencing also resulted in increasing mRNAs related to liver fibrosis, including Col1a1, Col3a1, Tgfβ1, Pdgfβ, Tgfβr1, Pdgfrβ, and Timp1." (PMID 31805036, 2019). "Many molecules and signalings have been documented to initiate HCs apoptosis and EMT in liver fibrosis, including TGFβ1, Notch and Hippo pathways." (PMID 31695787, 2019). "Further, therapeutic administration of the αV integrin-specific-RGD peptidomimetic antagonist CWHM 12 also reduced pre-existing hepatic fibrosis, most probably again due to lowered TGFβ1 activation." (PMID 31771248, 2019). "It has been reported that TGFβ1 and NF-κB were both involved in rat liver fibrosis and liver cirrhosis, in which the expression of TGFβ and the nuclear translocation of NF-κB were both required." (PMID 29980933, 2019). "HSCs, the major mesenchymal cell type in the liver, are well known for their critical functions in liver fibrosis, which is activated by TGFβ1." (PMID 29416678, 2018). "The functional roles of ITGBL1 were clarified by using in vitro experiments, which showed that ITGBL1 promotes HSC activation and liver fibrosis by upregulating TGFβ1." (PMID 28262670, 2017). "In this CCl4-induced model of liver fibrosis, multifunctional TGFβ1 can mediate the EMT and/or activation of HSCs leading to active myofibroblasts, which are marked by enhanced α-SMA expression." (PMID 28458469, 2017). "In summary, hepcidin suppresses liver fibrosis by impeding TGFβ1-induced Smad3 phosphorylation in HSCs, which depends on Akt activated by a deficiency of ferroportin." (PMID 28004654, 2016).
liver fibrosis (continued). "We found that ghrelin treatment ameliorated CCl4- and BDL-induced liver fibrosis via inhibition of the TGFβ1/Smad3 and NF-κB pathways, as well as autophagy suppression." (PMID 26378522, 2015). "Conditional genetic deletion of PP2Acα attenuated liver fibrosis in the mice following chronic CCl4 treatment, probably through impairing TGFβ1/Smad profibrotic signaling pathway." (PMID 25710025, 2015). "Liver epithelial to mesenchymal transition (EMT) was induced by transforming growth factor beta 1 (TGFβ1) to evaluate in vitro liver fibrosis." (PMID 25502575, 2014). "The administration of solubilized CoQ10 in mice inhibited dimethylnitrosamine (DMN)-induced liver fibrosis by alleviating TGFβ1 expression." (PMID 24691097, 2014). "Secretion of TGFβ1 and activation of myofibroblasts play a critical role in the pathogenesis of liver fibrosis of different etiologies." (PMID 25100997, 2014). "Recombinant gp120 also increases expression of transforming growth factor b1 (TGFb1) – a key mediator of liver fibrosis – and HCV replication in vitro." (PMID 24586227, 2014). "The identification of the Hepatic Fibrosis/Hepatic Stellate Cell Activation pathway (identified by Vegfa, Il1a, Tgfb1, Tgfa, Il1b, and Pgf) is interesting, as the polarization of M2 macrophages is a critical component of this pathology." (PMID 24156623, 2013). "Transforming growth factor beta 1 (TGFβ1) plays a key role in the progression of liver fibrosis, and Huangqi decoction and its ingredients (IHQD) markedly ameliorated hepatic fibrotic lesions induced by ligation of the common bile duct (BDL)." (PMID 22471627, 2012). "Transforming growth factor beta 1 (TGF-β1), a critical fibrotic cytokine for hepatic fibrosis, is a potent EMT inducer." (PMID 23236489, 2012). "Hepatocytes, cholangiocytes, and myofibroblasts in the cholestatic liver injury released TGFβ1, and activated TGFβ1 receptors can accelerate liver fibrosis." (PMID 22471627, 2012). "These beneficial effects of curcumin, delaying the progression of hepatic fibrosis, involved inhibiting the TGFβ1/Smad signalling pathway and decreasing CTGF expression." (PMID 22978413, 2012). "TGFB1 is also the strongest known inducer of fibrogenesis in the effecter cells of hepatic fibrosis and can stimulate the adipocyte transformation." (PMID 22811744, 2012). "c-Jun is a subset of AP1, which can stimulate transcription of a wide variety of genes involved in hepatic fibrosis, such as Col-I and TGFβ1." (PMID 23243430, 2012). "TGFβ1 and TGFβ2 are key cytokines in the development of liver fibrosis that can be expressed in a variety of cells including activated stellate cells, myofibroblats, macrophages and activated cholangiocytes." (PMID 21209952, 2010). "The inhibition of TGFβ1 and TGFβ2 expression and activation has been demonstrated to attenuate liver fibrosis, including biliary fibrosis." (PMID 21209952, 2010). "In this study, we induced LX-2 cells to establish a liver fibrosis model using 10 ng/mL of TGFβ1." (PMID 40148434, 2025). "At the molecular level, hepatic stellate cell (HSC) activation plays a pivotal role in the pathogenesis of liver fibrosis, with transforming growth factor beta-1 (TGF-β1) serving as a key activator through both the canonical (SMAD-dependent) and non-canonical (non-SMAD) pathways." (PMID 40244247, 2025). "Similarly, the levels of mRNA related to liver fibrosis (Col1A1, Acta2, Timp1, and Tgfb1) were significantly increased in the DM group, which were significantly reduced by the LFD treatment." (PMID 41374037, 2025). "In recent decades, liver fibrosis has been rigorously investigated in in vitro models (LX-2 cells and human primary HSCs), often through TGFβ1 stimulation, which elicits a response in the HSC phenotype and a shift in gene expression towards a fibrotic phenotype." (PMID 40564168, 2025).
liver fibrosis (continued). "Taken together, GSH could improve the engraftment efficiency of ADSCs in liver fibrosis by targeting TGFβ1/SMAD3/NOX4 signaling pathway, which provides a new theoretical basis for GSH enhancing ADSC engraftment efficiency in liver diseases." (PMID 40060764, 2025). "Additionally, mRNA levels of fibrosis markers, COL1A1 and TGFB1, were elevated during hepatic fibrosis, alongside an increase in CXCR6 expression." (PMID 40822973, 2025). "The notably higher AUC values of CD5L and TGFβ1- in comparison with APRI- suggest that while APRI can serve as a valuable screening tool for liver fibrosis, there may be limitations in its specificity compared to more sensitive markers." (PMID 40647574, 2025). "Furthermore, TQ stops the development of liver fibrosis by suppressing transforming growth factor-beta 1 (TGF-β1), a key mediator of fibrogenesis, and inhibiting collagen deposition, suggesting potentially effective treatment for fibrotic liver diseases." (PMID 40872538, 2025). "Furthermore, increased hepatic Tgfb1 gene expression observed in livers of CCl4‐injected Foxo1S273D mice further confirms the role of Foxo1 in regulating TGF‐β1 in liver fibrosis." (PMID 40479577, 2025). "Similarly, the expressions of the genesCOL1A1,COL3A1,ACTA2,DES,TGFβ1, andVIM, which are involved in liver fibrosis, increased in liver organoids treated with 100 mM and 200 mM ethanol." (PMID 38818583, 2024). "Activation of hepatic stellate cells after Alpha-1 antitrypsin deficiency may be due to increased levels of pro-fibrogenic molecules such as transforming growth factor beta 1 in liver fibrosis of mice." (PMID 38440292, 2024). "Furthermore, the downregulation of TGFβ1-induced Smad2/3 activation attenuated liver fibrosis and decreased morbidity and mortality among patients with chronic liver inflammation." (PMID 38654054, 2024). "In murine models of liver fibrosis induced by chemical compounds such as CCl4, the toxic effect is massive, with strong hepatocyte necrosis, exacerbated inflammatory response and a saturating release of TGFβ1." (PMID 39074160, 2024). "As for cellular function, both rEgE2D2 and rEgE2N could promote the proliferation and migration of TGFβ1-induced LX-2 cells, indicating that the entry of EgE2D2 and EgE2N into the liver tissue facilitated hepatic fibrosis development." (PMID 38643149, 2024). "TNF-α promotes TGFβ1-induced HSC activation to affect the progression of liver fibrosis." (PMID 39407108, 2024). "The inverse relationship between MEG3 and TGFβ1 further suggested the protective effect of MEG3 could extend to hepatic fibrosis in which MEG3 suppressed αSMA expression by indirectly antagonising TGFβ1." (PMID 39872125, 2024). "Moreover, FN1, COL1, and iNOS axis-mediated liver fibrosis were caused by DOX, and our data documented the fibrotic effect of DOX via the upregulation of VEGF, Wnt7b, β-catenin, FN1, Col-1, TGFβ1, iNos, and Bax in the DOX group." (PMID 37296647, 2023). "TGFβ1 and Col1a1 were analyzed as factors involved in liver fibrosis." (PMID 36835211, 2023). "C5 loss alleviated hepatic fibrosis and downregulated the expression levels of α-SMA and TGFβ1." (PMID 37227481, 2023). "A relationship between PAR-2 and TGFβ1 has also been found in liver fibrosis and kidney fibrosis." (PMID 37786576, 2023). "A gene cluster that was significantly downregulated in the Yap/Wwtr1 knockdown group contained genes primarily regulated by Tgfβ-1 and related to “hepatic fibrosis”, Stat3 pathway, and Th2 pathway— illustrating suppression of pro-fibrotic genes with depletion of Yap and Wwtr1." (PMID 36998974, 2023).
liver fibrosis (continued). "Liver fibrosis induced by N-Nitrosodimethylamine treatment in rats was associated with decreased circulating Se, decreased hepatic GSH and GPx, and increased circulating IL-6 and TGFβ1 cytokines." (PMID 37107278, 2023). "Interestingly, L-THP has been shown to exert anti-fibrotic effects by inhibiting autophagy and the TGFβ1/Smad pathway in hepatic fibrosis in mice and cell models." (PMID 37446633, 2023). "In the pathogenesis of liver fibrosis, these processes are regulated by several profibrogenic cytokines; however, the transforming growth factor-beta 1 (TGF-β1) signaling plays a pivotal role since it is responsible for the activation of myofibroblasts and the regulation of ECM homeostasis." (PMID 36672739, 2023). "In PE-treated dKO liver, there was no change in the level of TGFβ1 precursor (43 kDa), but collagen 1α1 was significantly reduced, suggesting that PE supplement–mediated reduction of TGFβ1 in the plasma could mitigate liver fibrosis." (PMID 37586586, 2023). "Furthermore, increased Sct signaling triggers biliary senescence/DR, and liver fibrosis by autocrine/paracrine pathways through upregulation of transforming growth factor β1 (TGFβ1) signaling." (PMID 36624475, 2023). "MSCs release the major soluble mediator milk fat globule-EGF factor 8 (MFGE8), which lowers extracellular matrix (ECM) proteins and liver fibrosis in mice by inhibiting transforming growth factor beta 1 (TGFB1)-mediated activation of hepatic stellate cells (HSCs)." (PMID 35663940, 2022). "Again, TGFβ may be involved in the induction of the EMT phenotype in liver fibrosis, via the activation of the TGFβ1/SMAD pathway." (PMID 35745656, 2022). "Furthermore, levels of liver transcripts of genes indicative of liver fibrosis, such as transforming growth factor beta 1 (TGFB1), actin alpha 2 (Acta2) (αSMA) and collagen type I alpha 1 (Col1a1), were measured." (PMID 35057565, 2022). "Moreover, genes involved in hepatic fibrosis (that is, TGFβ1, COL1A1 and αSMA) were markedly increased in individuals with NASH compared with lean individuals or those with NAFLD and were also positively correlated with senescence markers." (PMID 35995996, 2022). "Transforming growth factor-beta 1 coordinates with HSCs to accelerates liver fibrosis." (PMID 34746195, 2021). "Furthermore, hepatic mRNA levels of fibrogenic genes (Acta2, Col1a1, Col3a1, Col4a1, Tgfb1, Mmp13 and Vim) were significantly upregulated in miR-223KO mice compared with WT mice, suggesting that miR-223 deletion accelerated liver fibrosis." (PMID 33867837, 2021). "AGAP2 seems to be involved in TGFβ1 signaling that could contribute to the progression of hepatic fibrosis, suggesting AGAP2 as a potential new molecular target for liver fibrogenesis." (PMID 34820440, 2021). "Also, miR-146a attenuates liver fibrosis by directly suppressing the profibrogenic effects of transforming growth factor-β1 (TGFβ1)." (PMID 33692799, 2021). "In Con A‐induced autoimmune liver‐damaged mice, abnormal HSC activation was accompanied by imbalance of Tgfb1 and Tgfb3 expressions in the early stage, which can line immune and hepatic fibrosis processes, leading to further switching and progressing of liver fibrosis." (PMID 33269546, 2021). "The expression of Tgfb3 increased earlier than Tgfb1 in vivo in the liver of mice with TAA‐induced experimental liver fibrosis, suggesting that Tgfb3 may be more important than Tgfb1 in initiating fibrogenesis." (PMID 33269546, 2021). "Evidence has shown that AGAP2 regulates profibrotic properties in liver fibrosis via TGFβ1." (PMID 34820440, 2021). "It is widely acknowledged that the TGFβ1 signaling axis plays a major role in liver fibrosis." (PMID 33754025, 2021). "Indeed, it inhibits the expression of α-smooth muscle actin, transforming growth factor beta 1 and collagen type I alpha 1 chain to reverse liver fibrosis." (PMID 33595821, 2021).